SNORD13P1 (small nucleolar RNA, C/D box 13 pseudogene 1)
Synonyms: U13; U13.32A; RNU13P1
Gene: Small nucleolar RNA gene on chromosome 22 (42,076,058 to 42,076,161, reverse strand). Ensembl gene ENSG00000238498.
Homologues: Orthologues: macaque SNORD13P1 (93% identical). Paralogues in human: SNORD13 (89% identical), SNORD13D (86% identical), SNORD13P3 (86% identical), SNORD13E (82% identical).